CLCN1 (chloride voltage-gated channel 1)
Diseases named in the same sentence as CLCN1 in open-access papers (continued):
Sharing a sentence is not in itself a finding about the gene and the disease.
myotonia congenita (continued). "Myotonia congenita (MC) is a common channelopathy affecting skeletal muscle and which is due to pathogenic variants within the CLCN1 gene." (PMID 33507632, 2021). "In our cohort, another noticeable phenomenon was that some probands harbored compound heterozygosity of two dominantly inheritable variants (case 15), which suggested the dosage effect of CLCN1 mutation responsible for myotonia congenita of Thomsen type." (PMID 34790634, 2021). "A patient presenting the symptoms of myotonia congenita was shown to bear a new heterozygous missense variant in exon 9 of the CLCN1 gene (c.1010 T > G, p.(Phe337Cys))." (PMID 33507632, 2021). "Patients and Methods: Five patients with myotonia congenita due to mutations in CLCN1 gene were enrolled, which were identified through trio-whole-exome sequencing or panel-based next-generation sequencing test." (PMID 34790634, 2021). "Variants in the CLCN1, encoding a chloride channel, can cause Myotonia Congenita that usually causes muscle weakness and cramps in infants." (PMID 33562224, 2021). "Loss-of-function mutations in the CLCN1 gene abolish or reduce ClC-1 plasma membrane currents, leading to myotonia congenita (MC), the most frequent hereditary skeletal muscle channelopathy in humans." (PMID 34208776, 2021). "Myotonia congenita is due to mutations in the CLCN1 gene (ClC-1 chlorine channel), located on the long arm of chromosome 7, in position 7q34." (PMID 32117024, 2020). "Myotonia congenita and hypokalemic periodic paralysis type 2 are both rare genetic channelopathies caused by mutations in the CLCN1 gene encoding voltage-gated chloride channel CLC-1 and the SCN4A gene encoding voltage-gated sodium channel Nav1.4." (PMID 32407401, 2020). "Over 200 mutations in the human skeletal muscle ClC-1 gene (CLCN1) on chromosome 7 have been linked to myotonia congenita, which can be inherited in an autosomal recessive (Becker type) or autosomal dominant (Thomsen type) manner." (PMID 32117034, 2020). "Mutations in the human CLCN1 gene, which encodes the ClC-1 channel, are associated with a hereditary skeletal muscle disease, myotonia congenita." (PMID 32117034, 2020). "Loss-of-function mutations in the human CLCN1 gene that instigate defective gating and proteostasis of the ClC-1 channel have been associated with the hereditary muscle disease myotonia congenita." (PMID 32466489, 2020). "The majority of CLCN1 mutations are associated with recessive inheritance, with about 20 or less causing dominant myotonia congenita." (PMID 32117034, 2020). "Myotonia congenita can be inherited in a dominant (Thomsen disease) and recessive form (Becker disease) and both are caused by pathogenic variants in the CLCN1 gene." (PMID 33092578, 2020). "Mutations in the human CLCN1 gene lead to involuntary muscle contractions caused by anomalous sarcolemmal action potentials, clinically known as myotonia congenita." (PMID 32117034, 2020). "Previous studies have indicated that CLC-1 determines up to 80% of the resting membrane conductance in skeletal muscles and the mutation of CLCN1 reduces chloride conductance and then result in myotonia congenita." (PMID 31396442, 2019). "Mutations in the human gene (CLCN1) encoding CLC-1 channels have been linked to the hereditary skeletal muscle disorder myotonia congenita, which manifests delayed muscle relaxation following voluntary contraction." (PMID 30487393, 2018). "This case report of autosomal recessive Myotonia congenita caused by a novel compound heterozygous mutation expands the genotypic spectrum of CLCN1 gene." (PMID 30243293, 2018). "Myotonia congenita is caused by loss-of-function mutations in the CLCN1 gene coding for the skeletal muscle chloride channel ClC-1." (PMID 27242528, 2016). "It is interestingly to note that a mutation at the analogous position in CLCN1, G233S, was associated with dominantly inherited myotonia congenita." (PMID 26042048, 2015).
myotonia congenita (continued). "Mutations in the muscle chloride channel gene (CLCN1) cause myotonia congenita, an inherited condition characterized by muscle stiffness upon sudden forceful movement." (PMID 26502825, 2015). "In individual F7, two additional variants were identified by whole exome sequencing in CLCN1, the gene implicated in Myotonia Congenita [MIM 255700]." (PMID 26471370, 2015). "In this study, we generated transgenic zebrafish expressing, under the control of a muscle specific promoter, human CLCN1 carrying mutations that have been identified in human patients suffering from myotonia congenita." (PMID 25083883, 2014). "In humans, myotonia congenita (MC) is characterized by mutations within CLCN1, a gene encoding the skeletal muscle voltage-gated chloride channel ClC-1." (PMID 25356766, 2014). "Mutations in CLCN1 as the genetic basis of myotonia congenita proved that ClC-1 indeed represents the adult skeletal muscle chloride channel." (PMID 25339907, 2014). "Myotonia congenita is a human muscle disorder caused by mutations in CLCN1, which encodes human chloride channel 1 (CLCN1)." (PMID 25083883, 2014). "So far, more than 100 different mutations in the CLCN1 gene have been identified in patients with myotonia congenita." (PMID 23424641, 2013). "Both dominant and recessive forms of myotonia congenita are caused by mutations in the CLCN1 gene whilst both PMC and SCM are caused by mutations in the SCN4A gene." (PMID 23810313, 2013). "Myotonia congenita (MC) is a genetic disease caused by mutations in the skeletal muscle chloride channel gene (CLCN1) encoding the skeletal muscle chloride channel (ClC-1)." (PMID 24349310, 2013). "Myotonia congenita, a hereditary muscle disorder caused by mutations in the human CLCN1 gene on chromosome 7, is characterized by muscle stiffness after voluntary contraction." (PMID 23424641, 2013). "For example, individual 6 harbored a maternally inherited variant in CLCN1 (MIM: 160800) (Myotonia congenita Thomsen), which might explain sleeping difficulties and muscular hypertonia." (PMID 39668183, 2025). "Loss of function mutations in the CLCN1 gene encoding ClC‐1 cause myotonia congenita (MC), a rare disease characterized by sarcolemma hyper‐excitability responsible for muscle stiffness after voluntary muscle contraction, which improves with consecutive movements and worsens with inactivity." (PMID 40568930, 2025). "All probands with unknown inheritance pattern and all but one of the probands with uncertain association with myotonia congenita carried compound heterozygous CLCN1 variants." (PMID 34529042, 2022). "CLCN1 mutations are reported to associate with myotonia congenita and spine phenotypes." (PMID 36675693, 2022). "We identified a cat genetically affected with Myotonia Congenita, an uncommon recessively inherited disorder manifesting as an inability of the muscles to relax after contraction, which is caused by a variant in the CLCN1 gene." (PMID 35709088, 2022). "Interestingly, loss-of-function mutations in the human CLCN1 gene encoding ClC-1 are associated with the skeletal muscle disease myotonia congenita and manifest aberrant proteostasis and gating of the Cl− channel." (PMID 34070744, 2021). "The NDMs are comprised of myotonia congenita (MC) due to mutations in the skeletal muscle chloride channel gene CLCN1 encoding CLC-1 as well as paramyotonia congenita (PMC) and sodium channel myotonia (SCM) caused by mutations in the skeletal muscle sodium channel gene SCN4A encoding Nav1.4." (PMID 32848354, 2020). "Moreover, the phenotype for some carriers of the p.R1460Q mutation in the primary Finnish family was complicated by the independent cosegregation of a known CLCN1 mutation p.R894X associated with recessive myotonia congenita." (PMID 30824560, 2019).
myotonia congenita (continued). "As a consequence, mutations in the CLCN1 gene cause dominant and recessive forms of myotonia congenita (MC), a rare skeletal muscle channelopathy caused by abnormal membrane excitation, and clinically characterized by muscle stiffness and various degrees of transitory weakness." (PMID 25964741, 2015). "Mutations in CLCN1 can lead to autosomal dominant or recessive myotonia congenita." (PMID 26502825, 2015). "Domestic cats genotyped for the CLCN1 mutation associated with myotonia congenita." (PMID 25356766, 2014). "Myotonia congenita is a skeletal muscle channelopathy reported to occur naturally in humans as well as mice, water buffalo, sheep, goats, dogs, cats, horses, pigs and cattle, for which associated variants in CLCN1 have been reported in each species except cattle which remains undetermined." (PMID 39765607, 2024). "Thus, sodium channel myotonia and paramyotonia congenita are both linked to gain-of-function mutations of the SCN4A gene coding for Nav1.4 sodium channel, while myotonia congenita (MC) is related to loss-of-function mutations in the CLCN1 gene, encoding the chloride channel ClC-1." (PMID 33013670, 2020). "The discovery of a variant (CLCN1 c.2665insA) known to cause myotonia congenita in the Australian Cattle Dog in another breed popular in Australia, the Border Collie, calls for an investigation of whether its presence is limited to a single line of dogs or is more widespread in the breed." (PMID 27525650, 2016). "Furthermore animal studies have shown greatest concentration of CLCN1 channels at the neuromuscular junction, which may explain the increased susceptibility of this region to pathological changes in patients with myotonia congenita." (PMID 23810313, 2013). "CLCN1 should therefore be considered a candidate gene for investigating suspected myotonia congenita if identified in new species or breeds." (PMID 39765607, 2024). "The most common entity identified in patients was myotonia congenita with variants in the SCN4A and CLCN1 genes." (PMID 38758368, 2024). "In myotonia congenita, sexual steroid hormones reflect testosterone modulation of CLCN1 chloride channel activity and affect clinical manifestations of myotonia congenita." (PMID 36011377, 2022). "Myotonia congenita (MC) is a rare genetic disease caused by mutations in the skeletal muscle chloride channel gene (CLCN1), encoding the voltage-gated chloride channel ClC-1 in skeletal muscle." (PMID 35170402, 2022). "The mutations in the voltage-sensitive chloride channel genes CNCNKB, CLCN1, CLCN5, and CLCN7 have been linked to Bartter syndrome, myotonia congenita, Dent disease, and osteopetrosis, respectively." (PMID 25794116, 2015). "In this study, we present results of sequence analysis of the CLCN1 gene performed in Czech patients with myotonia congenita." (PMID 24349310, 2013). "Despite these findings, patients with myotonia congenita and related animal models do not typically show central neurological symptoms and very few cases of CLCN1 mutations associated with seizures have been reported." (PMID 40223930, 2025). "Myotonia congenita has been reported in eight non-laboratory animal species, with a variant in CLCN1 confirmed in seven species." (PMID 39765607, 2024). "Myotonia congenita has dominant and recessive forms, both caused by mutations in CLCN1 that result in reduced function of the encoded skeletal muscle chloride channel ClC-1.3,4 Sequencing of CLCN1 has become integral to confirming myotonia congenita diagnosis following clinical assessment." (PMID 34529042, 2022). "The CLCN1 gene is a good example in the recessive or dominant myotonia congenita." (PMID 35955641, 2022). "Mutations in CLC-1, encoded by CLCN1 gene (RefSeq NC_000007.13), lead to either the autosomal dominant form (Thomsen's disease: OMIM 160800) or the recessive form (Becker's disease: OMIM 255700) of myotonia congenita (MC)." (PMID 36081873, 2022).
myotonia congenita (continued). "ClC-1, which is a plasma membrane-bound chloride channel encoded by the CLCN-1 gene, is particularly known for its high Cl− conductance, its expression in skeletal muscles, and its genetic mutations causing myotonia congenita." (PMID 29765304, 2018). "All patients of our study are heterozygous with two distinct CLCN1 mutations on each allele, whereas relatives with only one mutation do not exhibit symptoms of myotonia congenita." (PMID 26502825, 2015). "Myotonia congenita has been reported in humans, mice and eight non-laboratory animal species (OMIA:000698), with likely causal variants identified in the CLCN1 gene in all species except cattle for which a single affected calf was reported and a likely causative variant not determined." (PMID 39765607, 2024). "Myotonia congenita is a non-dystrophic hereditary myopathy associated with reduced chloride conduction in skeletal muscle due to variants in the chloride voltage-gated channel 1 (CLCN1)." (PMID 39765607, 2024). "The diagnosis of myotonia congenita was confirmed through distinctive electromyography (EMG) findings, which were further supported by genetic testing revealing a homozygous mutation c.1445G>A in exon 13 of the CLCN1 gene, indicating autosomal recessive inheritance." (PMID 37489215, 2023). "For 8/10 pedigrees where the association with myotonia congenita was uncertain the inheritance was reported dominant but the proband carried two CLCN1 variants and it could not be confirmed which variant was dominant." (PMID 34529042, 2022). "SNPs analyses of CLCN1 in cats with and without myotonia congenita." (PMID 25356766, 2014). "However, it could be due to an incidental coexistence of myotonia congenita rather than an additional symptom of SPG11-HSP, given that a pathogenic CLCN1 mutation was identified." (PMID 37396771, 2023). "Although pathogenic CLCN1 variants are well-known modifiers of the disease phenotype in both DM1 and DM2, they are generally identified in a heterozygous state among DM patients which is normally not sufficient to cause the recessive form of myotonia congenita." (PMID 34501382, 2021).
Becker disease (13 papers, 2013 to 2025). "The CLCN1:c.2680C > T (p.Arg894*) gene is the most frequent pathogenic variant occurs in a homozygous or heterozygous compound state causing autosomal recessive myotonia congenita (Becker disease) in Polish patients." (PMID 38758368, 2024). "What is more, the c.1649C>T (p.T550M) variant has also been observed in combination with another CLCN1 variant in several individuals affected with autosomal recessive myotonia congenita." (PMID 34790634, 2021). "Homozygous or compound heterozygous pathogenic variants in the CLCN1 gene lead to recessive MC also known as Becker disease." (PMID 33092578, 2020). "Autosomal recessive Myotonia congenita (Becker’s disease) is caused by mutations in CLCN1 gene, which is located on the 7q35 chromosomal region and contains 23 coding exons." (PMID 30243293, 2018). "Both recessive (Becker’s disease) or dominant (Thomsen’s disease) MC are caused by mutations in the CLCN1 gene encoding the voltage-dependent chloride ClC-1 channel, which is quite exclusively expressed in skeletal muscle." (PMID 26007199, 2015). "Mutations of CLCN1 result in either autosomal dominant (Thomsen disease) or autosomal recessive (Becker disease) MC, and a subset have been found to cause both recessive and dominant MC (semidominant mutations)." (PMID 24349310, 2013). "Mutations of CLCN1 result in either autosomal dominant MC (Thomsen disease) or autosomal recessive MC (Becker disease)." (PMID 24349310, 2013). "Autosomal recessive Myotonia congenita (Becker’s disease) is caused by mutations in the CLCN1 gene." (PMID 30243293, 2018).
epilepsy (8 papers, 2014 to 2025). A brain disorder characterized by episodes of abnormally increased neuronal discharge resulting in transient episodes of sensory or motor neurological dysfunction, or psychic dysfunction. "Overall, although several studies have suggested a possible association between CLCN1 mutations and epilepsy, particularly through the presence of ClC-1 in the brain tissue, the current understanding remains limited." (PMID 40223930, 2025). "Some studies reported polymorphisms or mutations in the chloride channel genes CLCN2 (ClC-2) and CLCN1 (ClC-1) in epileptic patients but the involvement of these channels in epilepsy remains controversial." (PMID 27242528, 2016). "Although CLCN1 is expressed in the brain and mutations have been reported in patients with epilepsy, the functional role of CLCN1 mutations in other neurologic phenotypes including ataxia remains unclear." (PMID 32466254, 2020). "A mutation in the CLCN1 gene is reported and it is hypothesized that this disease-producing mutation is the cause of the seizure disorder in this patient." (PMID 27266866, 2016). "Currently, mutations in the CLCN1, CLCN2, CLCN3, CLCN4, and CLCN6 genes have been reported to be associated with various forms of epilepsy." (PMID 40223930, 2025). "Recent massive parallel sequencing for patients with sporadic epilepsy of unknown etiology identified SNVs in the chloride channel genes, CLCN1 and CLCN2, suggesting an association of CLCs with epilepsy." (PMID 25794116, 2015). "Indeed, the CLCN1 gene has been recently proposed as a candidate gene for epilepsy." (PMID 25964741, 2015).
congenital myotonia (7 papers, 2020 to 2025). Myotonia congenita (MC) is a genetic neuromuscular channelopathy which usually presents in early childhood resulting in a delay of skeletal muscle relaxation following contraction. "The sister of F4P4 was diagnosed with congenital myotonia caused by a homozygous pathogenic variant in CLCN1 (c.1696G>A p.(Ala566Thr))." (PMID 39923201, 2025). "More than 300 CLCN1 pathogenic variants have been found in association with congenital myotonia, inherited as recessive or dominant traits (with complete or incomplete penetrance)." (PMID 39712484, 2024). "Characterization of patients affected by recessive congenital myotonia carrying different CLCN1 mutations." (PMID 32655465, 2020). "We will report a rare case of association of pathogenic variants on PNPLA2 and CLCN1 genes with a mixed phenotype of NLSD-M and a subclinical form of Thomsen’s congenital myotonia." (PMID 37106355, 2023).
myotonic dystrophy type 1 (7 papers, 2016 to 2025). Steinert disease, also known as myotonic dystrophy type 1, is a muscle disease characterized by myotonia and by multiorgan damage that combines various degrees of muscle weakness, arrhythmia and/or cardiac conduction disorders, cataract, endocrine damage, sleep disorders and baldness. "In myotonic dystrophy type 1 and 2 (DM1 and DM2), for example, mutations in the DMPK and ZNF9/CNBP genes, respectively, disrupt the alternative splicing of the CLCN1 gene, creating a secondary reduction in sarcolemmal ClC-1 protein expression and current density." (PMID 32117034, 2020). "However, disease-associated reduction of functional pool of MBNL1 results in exon 7a inclusion and NMD-based turnover of CLCN1 transcript which manifests in reduced chloride ion conduction and myotonia affecting skeletal muscles in myotonic dystrophy type 1 (DM1)." (PMID 32708277, 2020).
myotonic dystrophy (6 papers, 2011 to 2025). An inherited progressive disorder affecting the muscles. "We report the case of a patient with genetically confirmed myotonic dystrophy co-segregating with a chloride voltage-gated channel 1 (CLCN1) gene mutation and partial seizures." (PMID 27266866, 2016). "Arg976Ter in the CLCN1 gene in a patient with myotonic dystrophy and generalised epilepsy, resulting in a truncation of the distal C-terminus of the protein." (PMID 40223930, 2025). "Concerning myotonic dystrophies, the co-segregation of DM2 mutation with mutations in CLCN1 or SCN4A genes were linked to unusual clinical findings." (PMID 30038349, 2018). "This supports other research that indicates that there is significant variability in CLCN1 transcripts in both muscle and brain tissues that could contribute to the phenotypic variability observed in patients with myotonic disorders." (PMID 27266866, 2016).